LINC00511 (long independently transcribed non-coding RNA 511)
Diseases named in the same sentence as LINC00511 in open-access papers (continued):
Sharing a sentence is not in itself a finding about the gene and the disease.
glioma (8 papers, 2019 to 2024). A benign or malignant brain and spinal cord tumor that arises from glial cells (astrocytes, oligodendrocytes, ependymal cells). "Reportedly, LINC00511 expression in glioma is up-regulated and associated with poor prognosis, and LINC00511 promotes tumor growth by modulating the miR-524-5p/YB1 molecular axis." (PMID 34937497, 2022). "The expression level of LINC00511 was not only highly expressed in the glioma tissues, but also overexpressed in the glioma cells detected by the RT‐PCR." (PMID 30973678, 2019). "Clinically, the expression of LINC00511 was measured using the RT‐PCR in tissue samples, demonstrating the high expression level in the glioma tissue specimens." (PMID 30973678, 2019). "More adequately, the ectopically high levels indicate the bad outcome of glioma patients with high level of LINC00511." (PMID 30973678, 2019). "Results indicated that LINC00511 was up‐regulated in glioma tissues and cell lines, moreover its overexpression positively correlated with the poor prognosis and advanced pathological stages." (PMID 30973678, 2019). "Subcellular fractionation indicated that the subcellular distribution of LINC00511 in the glioma cells was a cytoplasmic element." (PMID 30973678, 2019). "The deepgoing mechanism by which LINC00511 regulates the glioma tumourous phenotype was investigated." (PMID 30973678, 2019). "In addition to this, the silencing of LINC00511 expression suppressed cell viability, proliferation, migration, and invasion, and accelerated the apoptosis of glioma cells via a suggested miR-15a-5p/AEBP1 axis." (PMID 34771513, 2021). "So, the data suggest that LINC00511 epigenetically sponges the miR‐124‐3p in the glioma cells." (PMID 30973678, 2019). "In vivo, the LINC00511 silencing could repress the tumour growth of glioma cells." (PMID 30973678, 2019). "Therefore, LINC00511 promoted the proliferation, invasion and tumour growth of glioma cells." (PMID 30973678, 2019). "In summary, our study discovered the LINC00511 overexpression, inspired by the transcription factor SP1, in the glioma cells." (PMID 30973678, 2019). "Overall, our finding illuminates that LINC00511 is induced by SP1 and accelerates the glioma progression through targeting miR‐124‐3p/CCND2 axis, constructing the SP1/LINC00511/miR‐124‐3p/CCND2 axis." (PMID 30973678, 2019). "LINC00511 enhance the tumourous phenotype via sponging the miR‐124‐3p and targeting CCND2 production, thereby providing a model for LINC00511‐mediated cellular regulation in glioma." (PMID 30973678, 2019).
lung adenocarcinoma (7 papers, 2017 to 2023). A carcinoma that arises from the lung and is characterized by the presence of malignant glandular epithelial cells. "In conclusion, this study demonstrated the potential mechanism of overexpressed Linc00511 as an oncogene in lung adenocarcinoma via construction of a lncRNA–miRNA–mRNA network." (PMID 35842617, 2022).
osteosarcoma (5 papers, 2019 to 2023). A usually aggressive malignant bone-forming mesenchymal neoplasm, predominantly affecting adolescents and young adults. "To explore the role of LINC00511 in osteosarcoma, we measured its levels in OS cells, detected variations in cell biological functions and investigated the underlying molecular pathways." (PMID 31386627, 2019). "Therefore, further studies are needed to further ascertain the biological functions of LINC00511 in osteosarcoma and the other malignant tumors." (PMID 32713253, 2020). "Although the vast majority of literature supports the notion that LINC00511 may function as an oncogene, the opposite results were reported in osteosarcoma." (PMID 32713253, 2020). "Additionally, they further demonstrated that upregulation of LINC00511 could impede the progression of osteosarcoma through inducing apoptosis and suppressing the migration and invasion of osteosarcoma cells." (PMID 32713253, 2020). "Except for a single study in osteosarcoma, other studies in this type of cancer and other cancers have reported upregulation of LINC00511 in tumoral tissues compared with their non-tumoral counterparts." (PMID 37124625, 2023). "LINC00511 was confirmed to be beneficial for osteosarcoma development via sponging miR-618 and increasing MAEL expression and may thus be considered a potential target for osteosarcoma therapy." (PMID 31386627, 2019).
colorectal cancer (4 papers, 2021 to 2024). A primary or metastatic malignant neoplasm that affects the colon or rectum. "Further, both LINC00511 and miR-31-5p are oncogenic noncoding RNAs in colorectal cancer (see Section 2.1.4 about LINC00511)." (PMID 34298879, 2021). "In colorectal cancer (CRC), the overexpression of LINC00511 accelerated CRC development by facilitating cell proliferation, metastasis, and stemness." (PMID 34771513, 2021). "LINC00511 was also reported to play an oncogenic role via upregulating and downregulating nuclear factor I/A (NFIA) and interleukin 24 (IL-24), respectively, in colorectal cancer." (PMID 34298879, 2021).
glioblastoma (4 papers, 2020 to 2023). The most malignant astrocytic tumor (WHO grade IV). "Previous research has reported that LINC00511 could regulate trophoblast cell proliferation, apoptosis, invasion, and autophagy through the mir-31-5p/homeobox A7 axis, and promote temozolomide resistance in glioblastoma cells." (PMID 37434634, 2023).
ovarian carcinoma (4 papers, 2019 to 2021). A malignant neoplasm originating from the surface ovarian epithelium. "Importantly, increased LINC00511 expression is associated with ovarian cancer patients’ poorer outcome." (PMID 31016892, 2019). "Further experimental validation and mechanistic investigation indicate that LINC00511 exerts oncogenic function in ovarian cancer cells through interacting with EZH2 and repressing P21 expression." (PMID 31016892, 2019). "After detecting the expression level of LINC00511 in the cytoplasmic and nuclear components of ovarian cancer cells, we found that LINC00511 is mainly distributed in the nucleus of ovarian cancer cells." (PMID 31016892, 2019). "Taken LINC00511, LINC01132, MIR762HG and RP11‐83A24.2 for example, ovarian cancer patients with higher LINC00511 and LINC01132 expression levels or lower MIR762HG and RP11‐83A24.2 expression levels had poorer outcome." (PMID 31016892, 2019). "Here, our qRT‐PCR results showed that down‐regulated LINC00511 could increase P21 expression in ovarian cancer cells." (PMID 31016892, 2019). "Moreover, we performed RIP assays and found that LINC00511 directly bound with EZH2 in ovarian cancer cells." (PMID 31016892, 2019). "LINC00511 plays an oncogenic function by interacting with EZH2 and repressing P21 expression in ovarian cancer cells." (PMID 34461858, 2021). "Importantly, the results of ChIP assay showed that EZH2 could bind to P21 promoter region, and knockdown of LINC00511 expression could decrease EZH2’s binding to P21 promoter region and H3K27me3 modification in ovarian cancer cell." (PMID 31016892, 2019).
head and neck squamous cell carcinoma (2 papers, 2020 to 2021). A squamous cell carcinoma that arises from any of the following anatomic sites: lip and oral cavity, nasal cavity, paranasal sinuses, pharynx, larynx, and salivary glands. "In GEPIA, with RP11-54H7.4, MIR31HG, LINC00152, and LINC00511 being upregulated and H19, CTD-2545M3.8, RP11-760H22.2, and RP4-791M13.3 being consistently downregulated in head and neck squamous cell carcinoma (HNSC)." (PMID 32923393, 2020).
thymoma (2 papers, 2020 to 2022). A neoplasm arising from the epithelial cells of the thymus. "It was found that LINC00511 overexpression was significantly associated with worse OS in adrenocortical carcinoma (ACC) (HR = 4.5; log-rank p-value = 0.00047), and thymoma (THYM) (HR = 7.00; log-rank p-value = 0.035)." (PMID 32698787, 2020).
cholangiocarcinoma (1 paper, 2024). A carcinoma that arises from the intrahepatic biliary tree (intrahepatic cholangiocarcinoma) or from the junction, or adjacent to the junction, of the right and left hepatic ducts (hilar cholangiocarcinoma). "This discovery revealed a novel regulatory mechanism, the LINC00511–YTHDF2–SOX2–LINC00511 positive feedback loop, that plays a critical role in the onset and progression of cholangiocarcinoma." (PMID 39445001, 2024). "This study not only elucidates the complex interplay between LINC00511, YTHDF2, and SOX2 but also proposes potential therapeutic targets within this regulatory axis for cholangiocarcinoma treatment." (PMID 39445001, 2024).
esophageal cancer (1 paper, 2022). A primary or metastatic malignant neoplasm involving the esophagus. "Likewise, LINC00511 expression attains a high level in esophageal cancer, and further enhancement of LINC00511 accelerates the process of proliferation and migration and hinders cell apoptosis." (PMID 35477702, 2022).
papillary thyroid carcinoma (1 paper, 2020). "In specification, LINC00511 had tight relations to cell proliferation, tumor metastasis and progression in papillary thyroid carcinoma." (PMID 31897240, 2020).
stomach adenocarcinoma (1 paper, 2025). "Research has found that LINC00511 is highly expressed in stomach adenocarcinoma and is associated with poor prognosis in patients." (PMID 40076759, 2025).
triple-negative breast carcinoma (1 paper, 2017). An invasive breast carcinoma which is negative for expression of estrogen receptor (ER), progesterone receptor (PR), and human epidermal growth factor receptor 2 (HER2). "Thus, LINC00511 may be a bona fide therapy target in triple-negative breast cancer." (PMID 28738804, 2017).
tumor (82 papers, 2016 to 2025). "LINC00511 expression was found to be higher in multiple cancers and high expression was associated with tumor progression." (PMID 40076759, 2025). "It has been proven that aberrantly upregulated LINC00511 in malignant tumors is strongly associated with tumor size, clinical stage, lymph node metastasis, and unsatisfactory prognosis." (PMID 34760707, 2021). "Third, LINC00511 can accelerate tumor progression through regulating several tumor-associated signaling pathways such as RXRA/PLD1, PTEN/AKT/FOXO1, p38, ERK1/2 and JNK pathways." (PMID 32713253, 2020). "LINC00511-deficient xenografts manifested obvious tumor weight suppression as compared to the si-NC group (P < 0.05)." (PMID 31434797, 2019). "However, there are currently several gaps in our understanding of the overall mechanism of action of LINC00511 in tumor occurrence and development, as well as its associated networks with other molecular events." (PMID 39206156, 2024). "The results of the present research suggested that the Linc00511–hsa-miR-625-5p–SEMA6A axis could be associated with tumor autophagy, drug resistance, and cell apoptosis in SKCM." (PMID 37434634, 2023). "We also discovered that LINC00511 influence the biological functions of CCA tumor cells, including cell proliferation, migration, invasion, and tumorigenicity." (PMID 39445001, 2024). "These vital factors in maintaining tumor stemness were markedly decreased after knocking down LINC00511, reinforcing the role of LINC00511 in affecting stemness." (PMID 39445001, 2024). "Collectively, these results underscore LINC00511's critical function in driving tumor cell migration, invasion, and subsequent metastasis." (PMID 39445001, 2024). "Knocking down LINC00511 can significantly downregulate Nanog expression and its downstream genes, inhibiting the formation and self-renewal capacity of tumor stem cells." (PMID 39206156, 2024). "Firstly, LINC00511 can act as a ceRNA, where it regulates the expression of target genes by interacting with microRNAs (miRNAs) and thereby affecting malignant tumor cells." (PMID 39206156, 2024). "Experimental results indicated that the migration potential of tumor cells was significantly reduced following LINC00511 knockdown, whereas LINC00511 overexpression notably enhanced this capacity." (PMID 39445001, 2024). "Our study particularly focused on how LINC00511 affects tumor stemness, which is deeply intertwined with the occurrence, development, and metastasis of tumors." (PMID 39445001, 2024). "The widespread subcellular localization of LINC00511 differs in different types of tumor cells and this is likely to reflect on its biological functions and regulatory mechanisms." (PMID 39206156, 2024). "Angiogenesis, essential for tumor growth and metastasis, was notably diminished after knocking down LINC00511 and amplified after overexpressing it." (PMID 39445001, 2024). "Secondly, LINC00511 can regulate its own or target gene expression via epigenetic modifications thereby promoting tumor occurrence." (PMID 39206156, 2024). "Thirdly, LINC00511 can exert effects at the transcriptional level, such as the regulation of target genes and related signaling pathways, thereby influencing tumor progression." (PMID 39206156, 2024). "Overall, the suppression of LINC00511 curtailed tumor growth and altered the expression of related biomarkers, providing crucial insights for understanding the molecular mechanism of CCA and advancing the development of new therapeutic strategies." (PMID 39445001, 2024). "Expression of LINC00511 was significantly upregulated (57-fold change) in SCLC tissues compared with adjacent non-tumor tissues." (PMID 37098483, 2023). "Through its interaction with EZH2, LINC00511 has been shown to encourage tumor development and suppress apoptosis." (PMID 37124625, 2023). "Linc00511 behaves as an oncogene, affecting tumor volume and tumor metastasis and contributing to poor survival rates." (PMID 35842617, 2022).
tumor (continued). "LINC00511 activity was discovered to be over-expressed in human tumor cell lines (MDA-MB-468, MCF-HGH) compared to MCF-10A control lines using RT-qPCR." (PMID 35790898, 2022). "In order to elucidate the potential function of linc00511 on DET-mediated tumor inhibition, two different siRNAs targeting linc00511 (si-linc00511-1 and si-linc00511-2) were applied to silence linc00511 expression." (PMID 35794978, 2022). "After 27 days, the tumor volume and weight in the Ad-sh-linc00511 + Ad-NC group were decreased compared with those in the Ad-sh-NC group due to downregulation of Linc00511." (PMID 35842617, 2022). "To further elucidate how Linc00511 affects tumor growth in vivo, we subcutaneously injected A549 cells stably transfected with Ad-sh-NC, Ad-sh-linc00511 + Ad-NC or Ad-sh-linc00511 + Ad-COL1A1 into the right flank of nude mice to establish a xenograft model." (PMID 35842617, 2022). "The role of LINC00511 in mediating tumor formation and metastatic potential remains to be investigated in animal models." (PMID 35893227, 2022). "To conclude, the present study firstly disclosed that LINC00511 facilitated GC tumour progression at both transcriptional and post‐transcriptional levels." (PMID 34427967, 2021). "In conclusion, we propose a mechanism by which LINC00511 induces the release of exosomes and promotes tumor progression." (PMID 34088337, 2021). "We also confirmed that LINC00511 expression was increased in tumor tissue, which was consistent with the TCGA database." (PMID 34088337, 2021). "The expression of LINC00511 with hormonal receptor status was significant for ER status, PR status, tumor size, LNM, and BC molecular subtypes." (PMID 34745973, 2021). "Knockdown of linc00511 impaired tumor proliferation in vivo and in vitro, concomitant with induction of cell apoptosis." (PMID 34760707, 2021). "It's obviously that LINC00511 expression is related to tumor size, T stage, Lymph node metastasis, AJCC stage and histological type from TCGA." (PMID 31897240, 2020). "Second, LINC00511 can regulate tumor suppressors or oncogenes by interacting with DNA methylation-related enzymes and transcriptional factors to facilitate tumor progression." (PMID 32713253, 2020). "Long intergenic non‐coding RNA 00511 (LINC00511) plays a pivotal role in tumour; however, the role of LINC00511 in GBM, especially in the epigenetic molecular regulation mechanism of EMT, is still unclear." (PMID 31856394, 2020). "Depleting LINC00511 reduced tumor cell proliferation, migration and invasion, slowed tumor growth, and accelerated cell apoptosis." (PMID 32042282, 2020). "For example, by interacting with miRNAs, several lncRNAs (including GAS5, XIST, NORAD, and Linc00511) modulate PC progression by enhancing the proliferation, migration and invasive capacity and angiogenesis of PC cells as well as tumor growth in vivo." (PMID 31488171, 2019). "Aberrations of LINC00511 expression perform important functions in tumorigenesis and tumor progression." (PMID 31434797, 2019). "The results showed that the LINC00511 expression level was higher in tumor tissues than in adjacent tissues (P<0.01)." (PMID 31386627, 2019). "In the light of our in vitro data that knockdown of linc00511 impaired tumour proliferation, concomitant with induction of cell apoptosis." (PMID 28984028, 2018). "According to the results of qPT‐PCR analysis, we verified the depletion of linc00511 in the xenotransplanted tumours from the shlinc00511 group." (PMID 28984028, 2018). "It is therefore reasonable to hypothesize that targeting LINC02188 and ROCR in the Basal subtype and targeting LINC00511 in the Her2 and LumB subtype could reduce RNA methylation modification levels to inhibit tumor development." (PMID 38408075, 2024).